ALB (albumin)
Diseases named in the same sentence as ALB in open-access papers (continued):
Sharing a sentence is not in itself a finding about the gene and the disease.
congestive heart failure (continued). "Advanced age, low BMI, history of congestive heart failure or time on HD before PD ≤ 3 months and peritonitis were the factors associated with increased risk, while use employee medical insurance and higher serum albumin associated with decreased risk for the technique failure." (PMID 35690721, 2022). "Decreased albumin levels are common in congestive heart failure (CHF), but little is known about its role in mortality risk in CHF." (PMID 36171266, 2022). "Advanced age, lower BMI, history of HD or congestive heart failure and peritonitis were the factors associated with increased risk for the technique failure, while using employee medical insurance to pay expenses and high serum albumin associated with decreased risk for the technique failure." (PMID 35690721, 2022). "Our investigations, which integrated albumin concentrations in evaluating the danger of congestive heart failure, revealed a distinct trend across various analytical frameworks." (PMID 41479744, 2026). "Second, in the ALIAS trial, patients treated with albumin experienced a higher incidence of pulmonary edema and congestive heart failure compared to those treated with saline." (PMID 40757028, 2025). "In a univariate linear regression model, age, CAD, and the presence of congestive heart failure were positively correlated with QTc, whereas a longer time on dialysis and higher levels of albumin and low-density lipoprotein predicted a shorter QTc interval." (PMID 38337348, 2024). "Onunivariate analysis, preoperative factors including right ventricularsystolic pressure (RVSP) (PH-severity marker), congestive heart failure,albumin, NLR, PLR, SII, and aortic cross-clamping (ACC) and cardiopulmonarybypass (CPB) times predicted poor outcome." (PMID 34859659, 2022). "It was reported that, in patients with congestive heart failure, the albumin infusion group had markedly higher in-hospital mortality (36.42% vs. 21.81%), longer ICU length of stay (LOS), and hospital LOS." (PMID 36337861, 2022). "Stratified by the BUN/ALB ratio, compared with the BUN/ALB ratio of < 0.249 group, there were more patients with congestive heart failure in the BUN/ALB ratio of ≥ 0.249 group (44.1% vs. 27.3%, P = 0.012)." (PMID 36522751, 2022). "In the landmark Randomized Evaluation of Mechanical Assistance for the Treatment of Congestive Heart Failure (REMATCH) trial model, platelet counts, albumin, INR, and AST were associated with 1-year mortality in the HF population with implantable devices." (PMID 33871375, 2021). "In particular, the GNRI, which considers albumin levels, is frequently employed as a nutritional index in patients with chronic heart failure." (PMID 32607637, 2021). "BMI, chronic heart failure, the Barthel Index, respiratory failure, hemoglobin levels and albumin levels, which were also identified as significantly different between survivors and non-survivors in the univariate analysis." (PMID 33619334, 2021). "With higher quartiles of serum chloride, there was a significant decreasing trend for diuretic use, eGFR, serum bicarbonate, serum albumin, serum calcium, and prevalence of congestive heart failure." (PMID 32375681, 2020). "In particular, older age, catheter vascular access, albumin <3.5g/dl, phosphorus <3.5mg/dl, cancer and congestive heart failure all were involved in the death rate increase." (PMID 32655743, 2020). "History of congestive heart failure, albumin level, C-reactive protein level, and age at dialysis initiation were the most important factors affecting the prediction for first-year mortality in both model 1 and model." (PMID 33118948, 2020). "Long-term bedridden status, congestive heart failure, CURB-65, glucose, heart rate and age were independent poor prognostic factors of 60-day mortality, while increased SaO2 and albumin levels were associated with better prognosis." (PMID 29699493, 2018).
congestive heart failure (continued). "The risk of WRN increased as the basal serum albumin level decreased and was strongly associated with highest quartile serum AST level at post INR elevation and the presence of congestive heart failure." (PMID 23560034, 2013). "A lower basal serum albumin, highest quartile serum AST level at post INR elevation, and congestive heart failure were associated with the occurrence of WRN." (PMID 23560034, 2013). "The C-reactive protein-to-albumin ratio (CAR), a marker of inflammation and nutritional status (calculated as C-reactive protein [CRP]/albumin [ALB]), is associated with increased mortality in congestive heart failure (CHF)." (PMID 40776958, 2025). "Both univariate and multivariable logistic models showed that VTC, comorbidities including congestive heart failure, and laboratory indicators including platelet, baseline creatinine, and albumin, SOFA, other nephrotoxic medications, and GCS score were all related to the development of VA-AKI." (PMID 38509460, 2024). "Specific covariates that were not well balanced included admission from a nursing home, international normalized ratio, dementia, hematocrit, albumin, independent baseline functional status, congestive heart failure, ASA physical status, and mortality probability (all SMDs ≥0.2)." (PMID 36322619, 2022). "Sufficient and powerful randomized, placebo-controlled trials are needed in congestive heart failure of intensive care unit to test whether supplementing endogenous albumin may prove to be an effective method to reduce short-term all-cause mortality." (PMID 36171266, 2022). "Low serum albumin is common in patients with chronic heart failure (HF)." (PMID 30637771, 2019). "Albumin, hemoglobin, ICU LOS, the proportion of VF, and congestive heart failure in the survival group were higher (P < 0.05)." (PMID 38658985, 2024). "Risk factors for hypernatraemia at presentation included age, institutionalization, congestive heart failure, dementia, higher SARS-CoV-2 Ct value, white cell count, C-reactive protein and lower eGFR and albumin levels (p < 0.001 for all)." (PMID 36769690, 2023). "The independent predictors of 60-day mortality were age, long-term bedridden status, congestive heart failure, CURB-65, glucose, heart rate, arterial oxygen saturation (SaO2) and albumin levels." (PMID 29699493, 2018). "Further forward multivariate analysis revealed a significant correlation between increases in LVMI and being male, a history of congestive heart failure, advanced CKD stages, high systolic blood pressure, and low serum albumin level." (PMID 21860616, 2012). "The NT-proBNP-to-albumin ratio (NTAR) emerges as a potentially clinically relevant composite biomarker that reflects both cardiac overload and systemic dysfunction in patients with chronic heart failure (CHF)." (PMID 41007652, 2025). "ALB therapy was associated with an increase in symptomatic ICH and pulmonary edema/congestive heart failure but this did not affect final outcomes." (PMID 26325387, 2015). "Other factors related to overall mortality included the timing from diagnosis until the first-dose antimicrobial therapy, septic shock status, presence of congestive heart failure, age >65 years, APACHE II score >25, platelet count < 100,000 per mm3, and serum albumin < 3.2 g/dL." (PMID 22919379, 2012). "CRP, albumin and hemoglobin were evaluated in 119 patients, divided into two disease groups, hematological (ones with diagnosis of non-Hodgkin lymphoma or Hodgkin disease) and non-hematological (solid tumor patients and patients with chronic heart failure)." (PMID 23294910, 2013). "The associations among Klotho (exposure), congestive heart failure (CHF; outcome), and renal function markers [estimated glomerular filtration rate (eGFR), blood urea nitrogen (BUN), uric acid (UA), and urine albumin-to-creatinine ratio (UACR); mediators] were investigated using mediation analysis." (PMID 35509269, 2022).
congestive heart failure (continued). "In cachectic patients with Congestive Heart Failure (CHF), combination therapy of the angiotensin-converting enzyme (ACE) inhibitor “enalapril”, Digoxin and diuretic increase subcutaneous fat and muscle bulk together with a significant raise in plasma albumin." (PMID 32102506, 2020).
renal dysfunction (183 papers, 1992 to 2026). "On the other hand, EUCAST and Queensland dosing recommendations were also associated with a high probability of expected toxicity in renal dysfunction subjects (PTA toxicity > 50% for any ALB and eGFR < 40 mL/min)." (PMID 33672057, 2021). "Altered albumin/creatinine ratios in urine was associated with eccentric hypertrophy, indicating an early relations hip between cardiac and renal dysfunction." (PMID 32049171, 2020). "Urinary albumin excretion is an important marker of renal dysfunction and cardiovascular disease risk, even at subclinical levels." (PMID 30349743, 2018). "In pre-dialysis CKD patients, plasma homoarginine concentration is associated with the severity of renal dysfunction as well as with biomarkers of protein energy wasting and inflammation (body mass index, serum albumin and C-reactive protein)." (PMID 24023762, 2013). "On the basis of the CRYCO findings, recently issued clinical guidelines recommended the avoidance of hyperoncotic dextran, HES, and albumin solutions because of the risk for renal dysfunction." (PMID 21029460, 2010). "Most reported risk factors are pretransplant renal dysfunction, low serum albumin, dysfunction of the liver graft, bacterial infections and reoperations." (PMID 20550662, 2010). "The red cell distribution width/albumin ratio also exhibited a significant positive correlation with proteinuria, indicating potential abnormalities in red blood cell dynamics associated with renal dysfunction." (PMID 37791152, 2023). "The decrease in serum albumin could be due to albuminuria, a condition associated with renal dysfunction caused by abdominal obesity." (PMID 36431836, 2022). "Patients with comorbidities, lower lymphocyte counts in hemogram, platelet count and serum albumin, high C-reactive protein level, and renal dysfunction may have higher risk for death." (PMID 33762058, 2022). "The present study demonstrated that the intake of a 400-mg single dose of ibuprofen followed by running a half-marathon caused some degree of renal dysfunction, as suggested by an increase in urinary creatinine, albumin, NGAL and the development of hematuria in recreational runners." (PMID 32492913, 2020). "Secondly we investigated whether U-NGAL and PDA were associated with AKI and renal dysfunction evaluated by fractional excretion of sodium and urine albumin in a cohort of very preterm neonates." (PMID 28068947, 2017). "Secondary, to investigate whether U-NGAL and PDA are associated with AKI and renal dysfunction evaluated by fractional excretion of sodium (FENa) and urine albumin in a cohort of very preterm neonates." (PMID 28068947, 2017). "In literature, patients with renal dysfunction, low albumin/poor intake, or prolonged broad-spectrum antibiotic exposure appear at greater risk." (PMID 41509895, 2026). "Higher inflammatory activity, lower serum albumin levels, increased left atrial volume, renal dysfunction, and elevated diastolic filling pressures were also associated with VT." (PMID 41682854, 2026). "Male mice developed sustained renal dysfunction, characterized by persistent proteinuria, a marked reduction in glomerular filtration rate, and progressive increases in urinary albumin/creatinine ratio, consistent with an ongoing functional decline." (PMID 41554063, 2026). "For laboratory markers, moderate-to high-specificity was observed for markers of inflammation (detectable CRP; specificity 77.9%), nutritional or inflammatory status (low albumin; specificity 72.2%), and renal dysfunction (reduced eGFR; specificity 86.4%)." (PMID 40804822, 2025). "Renal dysfunction, a common complication of repeated paracentesis, was particularly rare in the patients treated with albumin." (PMID 40662011, 2025). "Half of the patients were anemic (Hb < 110 g/L) and had decreased serum albumin levels, with renal dysfunction observed in 40% of the patients." (PMID 41614836, 2025).
renal dysfunction (continued). "Meta-analyses have similarly confirmed albumin’s role in reducing hyponatremia, renal dysfunction, and mortality in selected patient populations." (PMID 41140983, 2025). "The associations between NT-proBNP and B2M, LDH, creatinine, and albumin imply a mechanistic link between inflammatory burden, renal dysfunction, and cardiac biomarker elevation." (PMID 41010591, 2025). "Adding to this, renal markers such as serum creatinine, eGFR, and urinary albumin-to-creatinine ratios were consistent throughout the groups, excluding the role of significant renal dysfunction in the prevalence of PE or ED." (PMID 40416166, 2025). "Evaluating denosumab-induced hypocalcemia requires albumin adjustment, the incidence of which is high among patients with severe renal dysfunction." (PMID 38360579, 2024). "In contrast, the serum albumin levels decreased (P < 0.001) and albumin-adjusted serum calcium levels increased (P < 0.001) with the degree of renal dysfunction." (PMID 38360579, 2024). "Vasoactive inotrope score for cardiac dysfunction, renal score for renal dysfunction, fibrosis-5 index, and lactate/albumin ratio for hepatic dysfunction were evaluated." (PMID 39767157, 2024). "When administering denosumab for bone metastases of solid tumors, we found that calcium monitoring with albumin adjustment is essential in patients with severe renal dysfunction to prevent overestimation of hypocalcemia." (PMID 38360579, 2024). "Despite these limitations, our study sheds light on the prevalence of hypocalcemia in patients with severe renal dysfunction and highlights the role of albumin in this context." (PMID 38360579, 2024). "Half of the patients had subnormal serum albumin levels indicating kidney disease or inflammatory disease, 20% of the patients had renal dysfunction, and 44% of patients were anemic (Hb < 110 g/L)." (PMID 39194701, 2024). "Low eGFR and high levels of ACR, creatinine, and albumin are indicators of reduced kidney function and potential renal dysfunction." (PMID 38347632, 2024). "The urinary albumin-creatinine ratio, an indicator of renal dysfunction, was elevated in the p62Endo group (p62fl/fl versus p62Endo: 9.080 versus 11.52, P = 0.0483)." (PMID 38365674, 2024). "In our study, we also found HGS positively correlated with physical activity, BMI, GNRI, hemoglobin, albumin, and uric acid, and negatively correlated with renal dysfunction." (PMID 38710751, 2024). "The elevated levels of ACR, urine albumin, serum creatinine, and reduced eGFR levels are indicators of renal dysfunction." (PMID 38347632, 2024). "Evaluating denosumab-induced hypocalcemia required albumin adjustment, and its incidence was high among patients with severe renal dysfunction." (PMID 38360579, 2024). "Conversely, participants with the highest SUA levels exhibited higher levels of BUN, creatinine, and urinary albumin, suggesting the presence of renal dysfunction." (PMID 38027101, 2023). "For instance, urinary albumin and creatinine levels are routine clinical markers for renal dysfunction." (PMID 37189804, 2023). "There were weak inverse correlations between plasma vitamin C and specific markers of renal dysfunction, including cystatin C, serum creatinine, and urine albumin (p < 0.01)." (PMID 35204128, 2022). "Fourth, several diseases, including liver and renal dysfunction, can result in decreased albumin levels and increased RDW, which can be a significant limitation of the study." (PMID 36399446, 2022). "HGB and ALB were significantly decreased in renal dysfunction group compared to other diabetic patients and healthy controls (P < 0.05)." (PMID 36129598, 2022). "In our cohort, we found that the BUN/ALB ratio of ≥ 0.249 group had more patients with AECOPD with renal dysfunction than the BUN/ALB ratio of < 0.249 group (62.7% vs. 43.8%, P = 0.009)." (PMID 36522751, 2022).
renal dysfunction (continued). "Renal dysfunction was defined as low estimated Glomerular Filtration Rate (eGFR < 60 ml/min/1.73 m2) or proteinuria (24-h protein excretion > 150 mg or urinary albumin-to-creatinine ratio > 3 mg/mmol)." (PMID 34559398, 2021). "Renal dysfunction was evaluated with the urinary albumin to creatinine ratio (UACR) (3.2 [2.0-4.6] vs. 3.6 [1.5-5.4] vs. 4.3 [1.9-6.6] mg/gr Crea) which was also similar in PA and EH and Controls." (PMID 34804057, 2021). "According with previous studies, patients with a maximum aortic diameter ≥ 5.5 cm, renal dysfunction or albumin amount ≤ 30 g/L were more likely to experience in-hospital mortality or organ malperfusion." (PMID 33653281, 2021). "CKD was defined as the presence of renal dysfunction (urine albumin-creatinine ratio ≥ 30 mg/g) or estimated glomerular filtration rate (eGFR) < 60 mL/min/1.73m2." (PMID 34966356, 2021). "ALB, NAG, SCr, 24 h urinary protein quantity, and eGFR were also factors associated with the progression of renal dysfunction." (PMID 32337271, 2020). "Renal dysfunction, as measured by higher serum creatinine and lower eGFR, was a strong predictor of low serum albumin in walk-PHaSST and OMG cohorts." (PMID 32776978, 2020). "The levels of urinary albumin excretion, blood creatinine, and urea nitrogen were detected to evaluate the diabetic renal dysfunction." (PMID 29682583, 2018). "Urinary albumin, blood urea nitrogen, and blood creatinine are commonly used to characterize the renal dysfunction in clinical diagnosis." (PMID 29682583, 2018). "The levels of urinary N-acetyl-β-D-glucosaminidase and albumin, which are markers of renal dysfunction, also decreased significantly after treatment." (PMID 28431542, 2017). "Renal dysfunction was defined as a decreased eGFR (<60 mL/min/1.73 m2) or albuminuria (urine albumin-to-creatinine ratio ≥ 30 mg/g)." (PMID 27213281, 2016). "Prior studies using a higher dose of albumin showed a similar statistically insignificant difference of renal dysfunction post LVP." (PMID 26150850, 2015). "She had renal dysfunction with a total urinary protein of 5.61 g/dL (56.1 g/L), serum albumin of 2.89 g/dL (28.9 g/L), urea nitrogen of 2.24 mg/dL (1.6 mmol/L), and serum creatinine of 0.54 mg/dL (48 μmol/L)." (PMID 21943175, 2011). "To evaluate the effects of DR on renal dysfunction in WFRs, we measured the urinary albumin excretion and Ccr." (PMID 21949662, 2011). "Low serum albumin level, renal dysfunction, and co-medications (corticosteroids) are the main factors usually blamed for raising metabolite concentrations." (PMID 21176194, 2010). "We examined the trends in urinary albumin excretion and renal dysfunction postpartum." (PMID 39857389, 2025). "Studies venturing into the roles of other biomarkers such as cystatin C, glycated albumin, and advanced glycation end-products, could provide a more comprehensive understanding of the correlation between glycemia and renal dysfunction." (PMID 41190245, 2025). "Furthermore, NLR has been identified as negatively correlated with eGFR and positively correlated with urinary albumin excretion, particularly in the early stages of renal dysfunction and albuminuria among diabetic patients." (PMID 41131907, 2025). "This may potentially introduce confounding by indication, particularly as patients with greater renal dysfunction might be more likely to receive albumin." (PMID 41021268, 2025). "Blood urea nitrogen (BUN), albumin, and creatinine are reliable indicators of renal dysfunction." (PMID 37971510, 2024). "Besides, heart disease patients often accompany with renal dysfunction, which affects albumin metabolism and leads to decreased levels." (PMID 39624213, 2024). "Furthermore, the ESRD group exhibited significantly lower bicarbonate levels, higher creatinine and phosphate levels, and lower serum albumin and eGFR levels, all of which are indicative of renal dysfunction." (PMID 38762513, 2024).